SLC7A5 (solute carrier family 7 member 5)
Diseases named in the same sentence as SLC7A5 in open-access papers (continued):
Sharing a sentence is not in itself a finding about the gene and the disease.
cancer (196 papers, 2008 to 2025). A tumor composed of atypical neoplastic, often pleomorphic cells that invade other tissues. "The expression of SLC7A5 has been studied in various cancers, and an elevated expression is associated with a poor prognosis." (PMID 39994841, 2025). "We further demonstrate that c‐Myc–IRP2–IRE axis is responsible for the upregulation of RTN4IP1, and identify SLC1A5, SLC3A2, and SLC7A5, three amino acid transporters implicated in cancer, as essential downstream effectors of RTN4IP1 in ESCC." (PMID 39757767, 2025). "Several studies have demonstrated poor patient outcomes associated with high SLC7A5 expression in cancers of various tissues." (PMID 38790003, 2024). "Pan-cancer analysis showed that SLC7A5 was significantly associated with the stage and grade of multiple tumors." (PMID 38790003, 2024). "Based on the evidence that SLC7A5 positively correlated with immunomodulators, TIIC, the cancer immune cycle, immune checkpoint and T cell inflammation scores, we also found that SLC7A5 was associated with the inflammatory tumor immune microenvironment." (PMID 38790003, 2024). "This mutation leads to upregulation of specific amino acid transporters (AATs) in cancer cells, such as SLC7A5 and SLC38A2, which are associated with enhanced amino acid uptake." (PMID 38459595, 2024). "L-type amino acid transporter 1 (LAT1), which is encoded by the SLC7A5 gene, preferentially transports large branched and aromatic neutral amino acids, and its expression is upregulated in various types of cancer cells." (PMID 36959802, 2023). "SLC7A5 is highly expressed in various cancers, and high SLC7A5 expression is associated with a poor prognosis in cancer patients." (PMID 36499136, 2022). "Interestingly, SLC7A5 has been identified as being upregulated in many cancers and closely linked with the growth and proliferation of cancer cells." (PMID 38987867, 2024). "Furthermore, SLC7A5 supplies essential amino acids to cancer cells and, thus, plays an important role in cancer-associated reprogrammed metabolic networks." (PMID 39309198, 2024). "SLC7A5 was found to be associated with TIIC in most cancers." (PMID 38790003, 2024). "Here, in many cancers, we found that SLC7A5 was associated with TMB and MSI." (PMID 38790003, 2024). "In addition, SLC7A5 is significantly associated with stemness index in many cancers such as CHOL, THYM, and BLCA." (PMID 38790003, 2024). "Consistent with this, increased expression levels of SLC7A5 have been observed in various types of cancer such as breast cancer, KRAS-mutated CRC, gastric cancer, lung cancer, pancreatic cancer, prostate cancer, melanoma, ovarian cancer and hepatocellular carcinomas, and esophageal cancer." (PMID 38459595, 2024). "Genetic variants of SLC7A5 have been associated with cancer pharmacology." (PMID 39143954, 2024). "SLC7A5 (LAT1) has been implicated in various cancers and may facilitate treatment resistance by modulating mTORC1 signaling, although its role in PSCC is unknown." (PMID 37509297, 2023). "However, although SLC1A5 is the major glutamine transporter, with high affinity and high capacity observed in many cancer types, other members of the solute carrier superfamily including SLC7A5 (LAT1) and SLC38A1/2 (SNAT1/2) have also been linked to tumor-specific glutamine uptake." (PMID 38641063, 2024). "Furthermore, we found that miR-126-3p regulates the expression of many cancer-related genes, including those encoding solute carrier family 7 member 5 (SLC7A5) and a disintegrin and metalloproteinase domain-containing protein 9 (ADAM9), and that it directly targets these genes." (PMID 26244545, 2015). "The MAT2A inhibitor, such as IDE397, selectively induces synthetic lethality in MTAP-deficient malignancies, while SLC7A5 inhibitors, such as JPH203, exert anti-cancer activity by blocking SLC7A5." (PMID 40430461, 2025). "SLC7A5 activates the Akt/mTOR pathway to immunosuppress the tumor microenvironment and enhance radioresistance of cancer." (PMID 40362545, 2025).
cancer (continued). "LAT1 (SLC7A5) transports large neutral amino acids and plays pivotal roles in cancer proliferation, immune response and drug delivery." (PMID 39952931, 2025). "It has proven to play a crucial role in cancer cell growth, as both pharmacological inhibition of SLC7A5 or its genetic silencing lead to a reduction in the proliferation of cancer cells and tumor growth in xenograft models." (PMID 40723225, 2025). "Cancers can display elevated levels of leucine, and leucine transporters such as LAT1 (SLC7A5) are frequently found overexpressed across various cancers." (PMID 40361504, 2025). "Increased serine synthesis or uptake of exogenous serine from the tumor environment by solute carrier family 1 member 4 (SLC1A4) and solute carrier family 7 member 5 (SLC7A5) is necessary for therapy resistance in many cancers." (PMID 40667288, 2025). "Using specific nanoparticles or liposomes that target SLC7A5 can enhance drug accumulation in cancer tissues, increasing drug bioavailability while reducing accumulation in non-cancer tissues to mitigate toxicity." (PMID 39973065, 2025). "mTORC1 controls cancer cell growth by activating SLC7A5, which provides leucine, an essential amino acid for cancer cells." (PMID 38790003, 2024). "The TCGA database expression data revealed that SLC7A5 is highly expressed in most cancers (such as UCEC, BRCA, CHOL, and others) compared to normal tissues after a comprehensive analysis." (PMID 38790003, 2024). "Unlike glucose transporter proteins, amino acid transporter proteins include a transporter protein whose expression is specialized for cancer cells, called solute carrier family 7 member 5 (SLC7A5)." (PMID 38790003, 2024). "It has been demonstrated that SLC7A5 expression is cancer-specific both by immunohistochemistry and PET utilizing SLC7A5-specific probes." (PMID 38790003, 2024). "SLC7A5, a member of the solute carrier family, plays a critical role in amino acid transport, which is essential for cancer cell metabolism and growth." (PMID 39628390, 2024). "Several studies showed that SLC7A5 presents a high tumor-specific expression in many types of cancer." (PMID 38402198, 2024). "SLC7A5 facilitates cancer initiation and progression by mediating the transport of amino acids and modulating the mTOR signaling pathway." (PMID 39610830, 2024). "SLC3A2 and SLC7A5 have been found to be highly expressed in various types of tumors or cancer cells, and they have been shown to exert pro-cancer effects in a variety of cancers through multiple pathways." (PMID 38267663, 2024). "The L-type amino acid transporter 1 (LAT1; SLC7A5), which preferentially transports large neutral amino acids, including most essential amino acids, is overexpressed in several types of cancer." (PMID 39143954, 2024). "SLC7A5 expression supports cancer progression, mostly by supplying essential amino acids to cancer cells, resulting in the activation of the mammalian target of rapamycin (mTOR) pathway to promote tumor proliferation." (PMID 38281999, 2024). "In thyroid cancer, pharmacological inhibition of SLC7A5 by JPH203 suppresses cancer cell proliferation and induces thyroid tumor growth arrest." (PMID 38705513, 2024). "As expected, SLC7A5 is expected to be a prognostic biomarker in various cancers, although its prognostic values are variable across cancers." (PMID 38790003, 2024). "A positive correlation was found between SLC7A5 and many anti-cancer immune steps in our own cohort (Xiangya cohort)." (PMID 38790003, 2024). "The function of SLC7A5 also activates the AKT/mTOR pathway which then mediates the radioresistance ability of cancer cells." (PMID 38705513, 2024).
cancer (continued). "SLC7A5 has been reported to be prognostic in several types of cancer, including breast cancer, pancreatic cancer, tongue cancer, renal cell carcinoma, and esophageal squamous cell carcinoma." (PMID 38722983, 2024). "L-type amino acid transporter 1 (LAT1/SLC7A5/CD98lc) is a major transporter of large neutral amino acids in cancer cells because of its predominant expression." (PMID 39270820, 2024). "This evidence again confirms that SLC7A5 is a significant predictor of cancer immunotherapy response." (PMID 38790003, 2024). "Decreased level of circulating amino acids is linked to increased uptake by cancer cells due to overexpression of amino acid transporters, including SLC1A5 (Gln uptake), SLC1A4 (Ser uptake), SLC7A5 (Leu, Ile, and Val uptake), or SLC7A1 (Arg uptake)." (PMID 38646441, 2024). "The SLC7A5 alias LAT1 receptor is upregulated in cancer cells because proliferation requires nutrients such as amino acids." (PMID 39125821, 2024). "In human cancer cell lines from colon, lung and kidney, SLC7A5 transport activity was the key growth-limiting step." (PMID 38722983, 2024). "For example, SLC7A5 expression increases as cancer progresses, resulting in higher levels of expression in high-grade tumors and metastasis." (PMID 39309198, 2024). "SLC7A5 is essential for cancer cell growth, and studies have demonstrated that pharmacological inhibition and knockdown/knockout of SLC7A5 inhibit the proliferation of cancer cells and xenograft tumors." (PMID 38790003, 2024). "SLC7A5-specific PET probes can be used not only as cancer diagnostics for false-positive results, but also as concomitant diagnostics for SLC7A5-targeted therapies to select patients with expected therapeutic benefit." (PMID 38790003, 2024). "In view of SLC7A5’s cancer specificity, it has been suggested as a potential molecular target in cancer treatment and diagnosis." (PMID 38790003, 2024). "Among early-stage cancers, SLC7A5 has been reported to be prognostic in stage I squamous cell carcinoma of the lung and pulmonary adenocarcinoma." (PMID 38722983, 2024). "SLC7A5 is highly expressed in various types of cancer, including NSCLC, and is correlated with poor prognosis in NSCLC patients." (PMID 38281999, 2024). "For example, cancer cells require a massive nutrient supply and SLC7A5, as an amino acid transporter, has been widely studied in various cancers, highlighting the importance of amino acid transport in cell proliferation and tumor growth 43-45." (PMID 38617535, 2024). "The high SLC7A5 group also showed significant upregulation of several anti-cancer TIIC effector genes." (PMID 38790003, 2024). "SLC7A5 is highly expressed in many cancer types and has been shown to be oncogenic, largely due to its ability to import leucine, which promotes cell growth by activating the AKT/mTOR pathway." (PMID 38281999, 2024). "For example, the use of BPA-based boron neutron capture therapy significantly enhances the efficiency of SLC7A5 (LAT-1)-mediated uptake of p-boronophenylalanine into cancer cells." (PMID 39850557, 2024). "An increasing number of studies have associated the transmembrane amino acid transporter SLC7A5, also known as large neutral amino acid-transporter 1 (LAT1), with worse outcome in cancer." (PMID 38082346, 2023). "Among the upregulated amino acid transporters in cancer cells, LAT1 (SLC7A5) is notable for cancer-specific expression." (PMID 37924140, 2023). "Inhibition of SLC7A5 inhibits protein synthesis by downregulating the mTORC1 signaling pathway and mobilizing the general amino acid control pathway in cancer cells." (PMID 37731509, 2023). "Upregulation of SLC7A5 provides cancer cells with advantages including increased access to necessary building blocks for protein synthesis." (PMID 38082346, 2023). "SLC7A5 is an amino acid transporter, and its expression in tumor cells contributes to the increased metabolism needed to meet cancer cell requirements." (PMID 37731509, 2023).
cancer (continued). "The data clearly shows the difference in gene expression distribution between two groups, with the expression of slc7a5 in cancer tissue higher than in normal tissue." (PMID 37298123, 2023). "Whereas KP enzymes preceding KMO, and also the 2 Trp transporters SLC1A5 and SLC7A5, are up-regulated in 32-46% of cancer types, KMO and subsequent enzymes show lesser expression, ranging from 3 to 18%." (PMID 36286592, 2022). "SLC7A5, as one of the main drivers of tumorigenesis, promotes protein synthesis in cancer cells by regulating the mTORC1 signaling pathway and the general amino acid control (GAAC) pathway." (PMID 36505791, 2022). "Recently, many studies have proven that SLC7A5 expression in adjacent tissues is lower than that in cancer tissues and is closely related to the growth and proliferation of tumor cells." (PMID 36505791, 2022). "The pharmacological inhibition or knockdown of SLC7A5 can inhibit the proliferation of cancer cells and the growth of xenograft tumors." (PMID 36090994, 2022). "We also report a function for the SCRIB/LLGL polarity complex in cancer cells as a regulator of membrane trafficking of the SLC7A5/SLC3A2 amino acid transporter complex." (PMID 35501367, 2022). "Mechanistically, LINC01614 directly interacts with ANXA2 and p65 to facilitate the activation of NF-κB, which leads to the upregulation of the glutamine transporters SLC38A2 and SLC7A5 and eventually enhances the glutamine influx of cancer cells." (PMID 36209111, 2022). "SLC7A5 is overexpressed in several types of cancer and is related to cancer progression and aggressiveness." (PMID 35328298, 2022). "L‐type amino acid transporter 1 (LAT1; SLC7A5), which preferentially transports large neutral amino acids, is highly upregulated in various cancers." (PMID 36071551, 2022). "SLC7A5 is overexpressed in the plasma membrane of aggressive cancer cells, and its expression level correlates with poor patient prognosis." (PMID 36324584, 2022). "The promoter region of SLC7A5 also contains the canonical binding sites for c-Myc, hence the increased expression of c-Myc in cancer that allows for constitutive expression of SLC7A5." (PMID 35163079, 2022). "SLC7A5 is highly expressed in most cancers including RCC where its expression levels inversely associate to OS and progression-free survival." (PMID 34200770, 2021). "Since SLC1A5, SLC3A2, and SLC7A5 are important for the metabolism, growth, and proliferation of cancer cells, these transporters have been targeted pharmacologically to block cancer cell growth and survival." (PMID 33953707, 2021). "It is generally believed that SLC7A5 is related to tumor development, angiogenesis, and poor prognosis of cancer patients as an ferroptosis regulator involved in energy metabolism." (PMID 34616431, 2021). "Four amino acid transporters have been found to be highly expressed in cancer, namely SLC7A5, SLC7A11, SLC1A5 and SLC6A14." (PMID 33849550, 2021). "SLC7A5 is overexpressed in a variety of malignant tumors, and it is positively correlated with adverse clinical outcomes in CCA." (PMID 34712611, 2021). "Many studies had reported that cancers vastly demand amino acid for ATP yielding, growth, and progression, through overexpression of SLC7A5 and SLC1A5." (PMID 34789172, 2021). "Solute carrier family seven member 5 (SLC7A5) as an amino acid transporter was overexpressed in multiple cancers including NSCLC, and its expression level was related to cancer progression and aggressiveness." (PMID 35096011, 2021). "c-Myc was shown to bind the promoters of SLC1A5 and SLC7A5 genes and upregulate their expression in cancer cells, indicating that c-Myc acts to sustain amino acid uptake through these transporters." (PMID 33953707, 2021). "The promoter of SLC7A5 has a typical binding site with C-Myc, and the high expression of C-Myc often leads to an increase of SLC7A5 expression level in cancer cells." (PMID 33849550, 2021).
cancer (continued). "In vitro experiments were conducted to investigate the effect of SLC7A5/SLC3A2 knockdown in the proliferation of cancer cells and to the sensitivity to tamoxifen." (PMID 32093034, 2020). "One of the key proteins responsible for the flux of EAAs in cancer cells is the plasma membrane transporter LAT1 (SLC7A5)." (PMID 32899180, 2020). "Data from the DepMap database show high expression levels of SLC1A5, SLC7A11, SLC38A2, and SLC7A5 in the selected cancer cell lines." (PMID 33400734, 2020). "SLC7A5 knockout cancer cell lines showed decreased P70S6K phosphorylation and compromised cell proliferation." (PMID 32867828, 2020). "SLC7A5 has been extensively studied in a variety of cancers and it is regulated by the oncogene c-MYC." (PMID 32200487, 2020). "As a critical amino acid transporter, SLC7A5 was mainly involved in regulating proliferation, apoptosis, and chemoresistance of cancer cells through activating the downstream AKT/mTOR pathway." (PMID 31803607, 2019). "3- Targeting of SLC7A5 protein to inhibit the essential amino acid uptake and metabolism, hence inhibiting the metabolic niche and induction of the oxidative stress in cancer stem cells." (PMID 30944375, 2019). "The hypoxia-inducible factor HIF2a upregulates SLC7A5, which plays a critical role in cancer growth and progression." (PMID 30558624, 2018). "In fact, SLC7A5 has been considered a potential therapeutic target for cancer treatment in humans and its specific inhibitor, JPH203 (KYT-0353) is currently undergoing a Phase I clinical trial in humans as a novel adjuvant treatment for solid tumors." (PMID 29422900, 2018). "Considering the similarity of cellular metabolism between cancer cells and activated immune cells, SLC7A5-mediated influx of AAs is likely to play a modulatory role in activated immune cells." (PMID 29422900, 2018). "Of note, SLC7A5 is predominantly expressed in various cancer cells, implicating its critical role for proliferation, growth, and survival of cells, whereas SLC7A8 is mainly expressed in normal tissue." (PMID 29422900, 2018). "It has been reported that SLC7A5 is highly expressed in a variety of cancers including oesophageal carcinoma, oral cancer and lung adenocarcinoma." (PMID 29566741, 2018). "Increased expression of SLC7A5 (solute carrier family 7, member 5) in many cancers correlates with alternative cell survival strategies in the hostile tumor microenvironment." (PMID 29796188, 2018). "To date, two amino acid transporters have been found to be over-expressed in cancers: SLC7A5 and SLC7A11." (PMID 30558624, 2018). "Microarray data pointed to elevated expression levels of SLC1A5 (ASCT2) and SLC7A5 (LAT1) in many cancers, which since has been confirmed in many studies and cell lines." (PMID 30072900, 2018). "It has been reported that SLC43A2 and SLC7A5 show increased expression in many types of cancer, and play a critical role in controlling protein translation and cell growth through the mTORC1 pathway." (PMID 28410417, 2017). "Both ADAM9 and SLC7A5 play important roles in several cancers and have been shown to be targeted by miR-126-3p." (PMID 26244545, 2015). "We also found that miR-126-3p targets genes involved in cancer, and directly regulates SLC7A5 and ADAM9 expression." (PMID 26244545, 2015). "SLC7A5 (also called LAT1) is overexpressed in many cancer types, and its expression levels are usually correlated to cancer progression, aggressiveness and prognosis." (PMID 23527086, 2013).